RPL26 (ribosomal protein L26)
Description:
Component of the large ribosomal subunit. The ribosome is a large ribonucleoprotein complex responsible for the synthesis of proteins in the cell.
Synonyms: L26; uL24; DBA11
Tractability: Small molecule: an approved drug acts on it; a structure with a bound ligand is known; a high-quality ligand is known. PROTAC: UniProt records ubiquitination sites on it; ubiquitination databases record sites on it; its protein half-life has been measured; a small molecule that binds it is known. Other modalities: a drug acting on it is in phase 2 or 3 trials.
Target class: Other cytosolic protein
Gene: Protein-coding gene on chromosome 17 (8,377,503 to 8,384,062, reverse strand). Ensembl gene ENSG00000161970.
Subcellular location: Cytoplasm
Subcellular location (Human Protein Atlas): Cytosol; Endoplasmic reticulum; Nucleoli
Pathways (Reactome):
Metabolism of proteins: Eukaryotic Translation Termination; Formation of a pool of free 40S subunits; GTP hydrolysis and joining of the 60S ribosomal subunit; L13a-mediated translational silencing of Ceruloplasmin expression; PELO:HBS1L and ABCE1 dissociate a ribosome on a non-stop mRNA; Peptide chain elongation; Ribosome Quality Control (RQC) complex extracts and degrades nascent peptide; SRP-dependent cotranslational protein targeting to membrane; ZNF598 and the Ribosome-associated Quality Trigger (RQT) complex dissociate a ribosome stalled on a no-go mRNA
Metabolism of RNA: Major pathway of rRNA processing in the nucleolus and cytosol; Nonsense Mediated Decay (NMD) enhanced by the Exon Junction Complex (EJC); Nonsense Mediated Decay (NMD) independent of the Exon Junction Complex (EJC)
Cellular responses to stimuli: Response of EIF2AK4 (GCN2) to amino acid deficiency
Developmental Biology: Regulation of expression of SLITs and ROBOs
Disease: Viral mRNA Translation
Metabolism: Selenocysteine synthesis
Gene Ontology:
Molecular function: mRNA 5'-UTR binding; protein binding; RNA binding; structural constituent of ribosome
Biological process: cellular response to gamma radiation; cellular response to UV; positive regulation of translation; regulation of translation involved in cellular response to UV; ribosomal large subunit biogenesis; rRNA processing; cytoplasmic translation; translation
Cellular component: cytoplasm; cytosolic large ribosomal subunit; cytosolic ribosome; extracellular exosome; membrane; nucleolus; nucleoplasm; ribonucleoprotein complex; cytosol; large ribosomal subunit; ribosome
Genetic constraint (gnomAD): Loss-of-function variants: 0 observed, 11.58 expected, observed/expected ratio (o/e) 0, 90% interval 0 to 0.26. The upper end of that interval is the gene's LOEUF score, 0.26, which puts it in group 1 of 6, group 1 being the genes least tolerant of losing a copy. Missense variants: 72 observed, 127.42 expected, observed/expected ratio (o/e) 0.57, 90% interval 0.47 to 0.69. Synonymous variants: 44 observed, 44.62 expected, observed/expected ratio (o/e) 0.99, 90% interval 0.77 to 1.27.
Homologues: Orthologues: guinea pig RPL26 (100% identical), mouse Rpl26 (100% identical), pig RPL26 (100% identical), rabbit RPL26 (100% identical), rat Rpl26-ps1 (97% identical), zebrafish rpl26 (96% identical), Drosophila melanogaster RpL26 (74% identical), Caenorhabditis elegans rpl-26 (61% identical). Paralogues in human: RPL26L1 (99% identical).
Diseases named in the same sentence as RPL26 in open-access papers:
RPL26 is named in the same sentence as 32 diseases in open-access papers, as found by Europe PMC text mining. Sharing a sentence is not in itself a finding about the gene and the disease. The quoted sentences say what the papers report.
Diamond-Blackfan anemia (7 papers, 2013 to 2023). A congenital aregenerative and often macrocytic anemia with erythroblastopenia. "In addition, human mutations in RPL26 are associated with diamond-blackfan anemia, a syndrome that includes growth retardation and skeletal abnormalities." (PMID 28454565, 2017). "The importance of critical interfaces between domains I, II and the 5.8S rRNA is further highlighted by the finding that key stabilizers of these sites include Rpl17 (RPL17 in humans) and Diamond-Blackfan anemia proteins Rpl26 (RPL26) and Rpl35 (RPL35) 24,25." (PMID 37037974, 2023). "In humans, mutations in RPs have been implicated in hematopoetic disorders, most notably Diamond-Blackfan anemia (DBA), which has been attributed to mutations in RPS19, RPS26, RPS24, RPS17, RPS10, RPS7, RPL35a, RPL26, RPL11, and RPL5." (PMID 23382688, 2013).
breast carcinoma (4 papers, 2015 to 2019). "In breast cancer, RPL26 expression is decreased in ductal carcinoma in situ (DCIS) and invasive DCIS as compared with normal breast tissue." (PMID 26687066, 2015). "This downregulation is particularly striking in breast cancer, where over 11 different microarray studies show RPL26 downregulation in breast cancer versus normal breast." (PMID 26687066, 2015). "To investigate whether Six1-mediated downregulation of RPL26 is relevant to human cancer, we performed western blot analysis on seven breast cancer patient-derived xenografts (PDXs)." (PMID 26687066, 2015).
pancreatic cancer (3 papers, 2018 to 2023). "The knockdown of RPL26 and RPL29 expression ablates the proliferation of human pancreatic cancer PANC-1 cells." (PMID 35050240, 2022). "To elucidate the process of RPL10 ufmylation involved in pancreatic cancer cells, we used immunoprecipitation to examine the interactions between co-substrates RPL10 and UFM1 as well as between RPL10 and E3 ligase UFL1, which could be similar to the ufmylating modifications of ASC1 and RPL26." (PMID 37280198, 2023).
Sepsis (2 papers, 2025). Sepsis is defined as life-threatening organ dysfunction caused by a dysregulated host response to infection. "Significant expression of the ribophagy-specific receptor NUFIP1 and autophagy-associated protein LC-3B was observed in CD4+ T lymphocytes after sepsis, with a corresponding decrease in the expression of ribosomal self-proteins ribosomal protein L7 (RPL7), RPL23, and RPL26." (PMID 40995563, 2025).
cardiac hypertrophy (1 paper, 2023). "In addition, the expression of Rpl26, a known substrate of UFMylation, was upregulated by ISO in NTg mice rather than in Tg-Ufm1 mice.These data indicated that Tnfaip2 may be a novel UFMylation-related gene that is associated with cardiac hypertrophy." (PMID 37980507, 2023).
congenital malformations (1 paper, 2020). "Furthermore, global deficiency in RPS10 and RPL26 genes is associated with growth retardation and congenital malformations." (PMID 33324640, 2020).
intrauterine growth restriction (1 paper, 2020). "The protein expression of ribosomal proteins RPL26 (RPL26) and Ribosomal Protein S10 (RPS10) was decreased and positively correlated to mTORC1 signaling and System A amino acid transport in human placentas collected from pregnancies complicated by intrauterine growth restriction (IUGR)." (PMID 33324640, 2020).
ischemic stroke (1 paper, 2019). A stroke disorder caused by obstruction of blood flow to the brain, due to thrombotic (local blood clot formation) or embolic (due to a blood clot or other material traveling from another site) event. "First of all, four proteins were involved in ribosome function during ischemic stroke, namely, RPL26, RPL17, RPL39, and RPS13." (PMID 31223330, 2019).
male infertility (1 paper, 2017). The inability of the male to effect fertilization of an ovum after a specified period of unprotected intercourse. "Other members of the Ubiquitin-specific peptidase family have in fact been associated with male infertility and also RPL26." (PMID 28345611, 2017).
renal agenesis (1 paper, 2023). Renal agenesis (RA) is a form of renal tract malformation characterized by the complete absence of development of one or both kidneys (unilateral RA or bilateral RA respectively), accompanied by absent ureter(s). "It is known that the RPL26 gene is associated with Diamond–Blackfan anemia 11, in which unilateral renal agenesis occurs." (PMID 37958966, 2023).
infection (13 papers, 2012 to 2025). The state of being infected such as from the introduction of a foreign agent such as serum, vaccine, antigenic substance or organism. "The severe limitations of the cellular model, together with a presumably low frequency of ER-stalled ribosome stalling during productive infection, explain our failure to conclusively demonstrate the occurrence of endogenous RPL26 UFMylation in induced LCLs." (PMID 39842454, 2025). "Previous studies comparing untreated HIV-infected individuals to healthy controls reported decreased expression of several ribosomal proteins, such as RPS27, RPL18A, RPL8, RPL26, RPL4, and RPS21, possibly reflecting impaired translational activity during active infection." (PMID 41226717, 2025).
cancer (8 papers, 2015 to 2025). A tumor composed of atypical neoplastic, often pleomorphic cells that invade other tissues. "This paradox also applies for mammalian cells: in two independently induced murine cancers, uL6/RPL9 and uL24/RPL26 encoding genes behave as tumor suppressors, whose mutation or loss promotes tumor progression." (PMID 29674660, 2018).
tumor (7 papers, 2015 to 2023). "While we observe a trend (P=0.06) towards a positive correlation between Six1 and miR-27a expression in human patient tumour data sets, the inverse correlation between Six1 and RPL26 appears to be much stronger in patient tumours." (PMID 26687066, 2015). "The clinical relevance of this interaction is underscored by the finding that Six1 expression strongly correlates with decreased RPL26 across numerous tumour types." (PMID 26687066, 2015). "In addition, gaining an understanding of how Six1 regulates miR-27a and RPL26 may be important in the future for identifying novel ways to resensitize tumours to Nutlin-3 therapies." (PMID 26687066, 2015).
cardiovascular disease (1 paper, 2024). "RPL21, RPL26, and RPL10A are important components of the large 60S ribosomal subunit with functions involved in cell proliferation, differentiation, apoptosis, and DNA repair, which have been associated with metabolism and cardiovascular disease progression." (PMID 38503760, 2024).
RPL26 also shares sentences with these, for which no sentence is quoted: viral infection (3 papers); aniridia (2); lymphoma (2); acute coronary syndrome (1); adenoma (1); Alzheimer disease (1); familial partial lipodystrophy (1); gastric cancer (1); HCMV infection (1); latent infection (1); Neonatal sepsis (1); parathyroid adenoma (1); prostate carcinoma (1); renal carcinoma (1); soft tissue sarcoma (1); Stroke (1); tauopathies (1); thymoma (1).